E2F1 (E2F transcription factor 1)
Diseases named in the same sentence as E2F1 in open-access papers (continued):
Sharing a sentence is not in itself a finding about the gene and the disease.
tumor (continued). "Further, we investigated the potential driver transcription factors (TFs) using SCENIC and found that E2F1 and CEBPB, associated with proliferation and stemness, were significantly upregulated in L‐side tumor cells, which further proved our above finding." (PMID 39716897, 2024). "Among eight E2F family members, E2F1 is the most potent activator of pro-apoptotic genes, thereby playing a central role in tumor suppression." (PMID 39595534, 2024). "The cell cycle in tumors is modulated by c-Myc, which regulates the expression of downstream target molecules, including cyclin D1/2, cyclin E1, CDK4, cdc25A, and E2F1, and promotes tumor growth." (PMID 39085875, 2024). "To assess the role of E2F1 in ATRT, we analyzed RNA expression of E2F1 in ATRT patient samples compared with normal brain or benign tumor/non-tumor tissues." (PMID 39437704, 2024). "Since E2F1 plays a crucial role in tumor suppression, it is important to elucidate how its activity is regulated." (PMID 39769018, 2024). "E2F1 has been shown to be involved in cell proliferation, differentiation, and apoptosis in various cancers, as well as tumor metastasis and chemotherapy resistance." (PMID 39045407, 2024). "Studies conducted previously have illustrated that E2F1 functions as a downstream target of miR-1205, providing further substantiation for the modulatory effects of the miR-1205/E2F1 signaling pathway on tumor progression." (PMID 38827325, 2024). "We report here that E2F1 physically interacts with active STAT3 and synergistically controls IL-6 expression to induce a tumor-associated inflammatory GRN that ultimately mediates metastatic traits and modulates the TME by releasing immunomodulatory factors." (PMID 39544930, 2024). "This function, paracrine regulation of cancer stem cells by WNT induction through E2F1/4 and tumour suppression through repression by RBs, extends the current view of the role of these cell autonomous cell cycle regulators." (PMID 38678032, 2024). "Turning to transcription factors in ACC, E2F1, and E2F3 are implicated in cell cycle regulation, with overexpression potentially driving excessive cell division and contributing to tumour growth." (PMID 38524085, 2024). "Their results showed the tumor-suppressive function of miR-106a in CRC potentially works through regulating E2F1 and caspase-9 expression." (PMID 37627777, 2023). "KAT2A has been found to be overexpressed in CRC and affects tumor metabolic reprogramming in CRC progression through epigenetic activation of E2F transcription factor 1 (E2F1)." (PMID 37697409, 2023). "E2F1, though a tumor suppressor in normal cells, in HNSCC promotes proliferation, invasion, suppresses squamous differentiation, and inhibits apoptosis." (PMID 38001610, 2023). "The E2F1 has been reported as a target for the retinoblastoma (Rb) pocket protein, which is essential for cell cycle regulation and a key mutant tumor suppressor in several malignancies." (PMID 36941595, 2023). "E2F1 can inhibit glucose oxidative metabolism in a variety of ways and promote the transformation of tumor cell metabolism from OXPHOS to aerobic glycolysis." (PMID 36994237, 2023). "E2F1 was significantly overexpressed in HCC tumor tissues and negatively correlated with the prognosis of patients." (PMID 36721155, 2023). "We further revealed that the increased sensitivity of tumor cells to oxaliplatin induced by CDK5 was restored by E2F1 knockdown, suggesting that CDK5-induced chemosensitivity is dependent on E2F1." (PMID 37990321, 2023). "Because E2F1 has tumor stimuli, its expression participates in preventing of proliferation and apoptosis of tumor cells." (PMID 36941595, 2023).
tumor (continued). "The ability to unlock their expression through pharmacological manipulation of PRMT5 and E2F1 activity enables what is potentially a powerful therapeutic approach to control the immunogenicity of tumour cells." (PMID 36841868, 2023). "This notion is in line with other reports, showing that E2F1 regulates other tumor features, such as metabolism, epithelial-mesenchymal transition, extracellular matrix remodeling and angiogenesis, ultimately promoting invasion and metastasis." (PMID 37980331, 2023). "The pooled results of all 17 studies conducted with tumor tissue showed that the increased expression of E2F1 was a favorable survival prognosis biomarker (HR = 1.21, 95%CI:1.16–1.26, I2 = 95.3%, *PHeterogeneity = 0.000)." (PMID 37277745, 2023). "Among E2F family members, E2F1 is the most potent activator of pro-apoptotic tumor suppressor genes, and is a critical regulator of tumor suppression." (PMID 36833320, 2023). "Specifically, low expression of ARRB1 promotes tumor growth enhancing the E2F1 survival function, while high expression of ARRB1 triggers E2F1 acetylation switching E2F1 function from pro-survival into pro-apoptotic." (PMID 36923256, 2023). "Knockdown of PIR in MCF7 and MDA-MB-231 cell lines caused a dramatic decrease in cell proliferation and xenograft tumor growth in mice by activating E2F1 and its target genes." (PMID 37647033, 2023). "A large number of essays have investigated the involvement of E2F1 in protein regulation and thus the impact of tumor development and prognosis." (PMID 37277745, 2023). "All relapsed patients showed many E2F1-positive nuclei in their tumour tissues, while NB in complete remission expressed a lower amount of E2F1 positive nuclei (p < 0.001, Mann–Whitney U test)." (PMID 36831529, 2023). "How to specifically amplify its cancer-inhibiting function while blocking its tumor-promoting function is a key question in targeting E2F-1 for cancer treatments." (PMID 36766831, 2023). "The transcription factor E2F1 has major roles in cell cycle control, checkpoint response and DNA replication and repair, which leads to DNA damage tolerance in tumour cells." (PMID 36720923, 2023). "In support of this possibility, we found that the mRNA and protein expression levels of E2F1 in the tumor tissues were higher than those in the paracancerous tissues." (PMID 37705754, 2023). "It is a direct target of the transcription factor Myc, a key oncogene, promoting tumor progression through the regulation of E2F1 expression." (PMID 36869839, 2023). "Mice that received an intratumoral injection of M/T-Exo showed increased tumor size, resistance to tamoxifen, and changes in E2F1 protein." (PMID 37237523, 2023). "Meanwhile, Western blot analysis of these tumor tissues confirmed that HR488B indeed effectively suppressed E2F1 protein expression in vivo, which was consistent with the results of in vitro studies." (PMID 38062013, 2023). "We firstly detected HR488B markedly downregulated E2F1 expression in an HCT116 xenograft tumor tissue by IHC staining." (PMID 38062013, 2023). "Pharmacological inhibition of PRMT5 or adjusting E2F1 levels qualitatively altered the repertoire of lncRNA-derived peptide antigens displayed by tumour cells." (PMID 36841868, 2023). "It was reported that hypoxia repressed BRCA1 expression by compromising the function of E2F1, resulting in tumor progression." (PMID 35155430, 2022). "Several studies have clarified the effect of the ubiquitin-proteasome pathway on the function of E2F1 and consequent tumour development 40, 50, 51, while posttranslational modification of E2F6 in HCC cells is poorly understood." (PMID 35844791, 2022). "In summary, these results showed the tumor-suppressive role of miR-532 in vivo functioning by targeting E2F1." (PMID 35440106, 2022). "E2F1 can affect cell growth factors by regulating NF-κB, thereby promoting tumor proliferation and anti-apoptosis." (PMID 36175803, 2022).
tumor (continued). "Together, these results indicate that SETD7 has a tumour-suppressing role in BC cells possibly by inhibiting aberrant expression of E2F1 and DNMT1." (PMID 35326563, 2022). "Compared with the NC, SNHG12 silencing slowed down tumor growth and reduced tumor weight, while further E2F1 overexpression boosted tumor growth and increased tumor weight." (PMID 35597996, 2022). "E2F transcription factor 1 (E2F1), a member of E2F family, functions as a tumor suppressor gene and can influence the progression of multiple types of cancers through regulating cell proliferation and invasiveness." (PMID 35030974, 2022). "POH1 functions in various biological processes, including cell differentiation, DNA break responses, aggresome disassembly, and E2F1 stability and tumor formation." (PMID 35100873, 2022). "Both of quercetin and emodin reduced expression of transcriptional factor, E2F1, to suppress tumor progression." (PMID 35152841, 2022). "Overexpression of RPL5 inhibited tumor cell growth and knockdown of E2F1 transcriptionally activated GRP78." (PMID 35293275, 2022). "In theory, restoring miR-532 levels in cancer would suppress oncogenic E2F1 expression, which in turn would weaken the inhibition of miR-532, thereby promoting the accumulation of miR-532 in cancer cells and delaying tumor growth." (PMID 35440106, 2022). "We identified three critical genes (FCN3, CDC20, and E2F1) involved tumor prognosis in HCC patients." (PMID 35402624, 2022). "Palbociclib, combined with Cetuximab decreased the tumor burden and significantly suppressed the expression of E2F1 and SEC61G while activating MHC-I in PDX model." (PMID 36712687, 2022). "Studies have found that E2F1 is highly expressed in a variety of tumor tissues and cells and plays a role of oncogenic gene." (PMID 35833075, 2022). "Activation of E2F1, together with inhibition of Let7, which has been reported to have a role in differentiation and tumor suppression, had the most significant P value for this gene signature." (PMID 36213002, 2022). "E2F1 is further renowned as a tumor promoter in numerous malignancies, due to its strong expressions in cancer tissues and cell lines, predicting undesirable prognoses, as well as enhancing cancer cell biological activities, metastasis, and metabolism." (PMID 35592867, 2022). "Our results showed that both mRNA and protein levels of E2F1 were up-regulated in GSCs tissues and cells in response to circASPM overexpression, exerting stronger tumor-promoting effects." (PMID 35371308, 2022). "In lung adenocarcinoma (LUAD), lncRNA HAGLR was identified as a tumor suppressor by recruiting DNMT1 to the promoter of E2F1 to inhibit tumor growth." (PMID 35292092, 2022). "As in other tumors, E2F1 also has a dichotomous role in PCa, acting as either an oncogene or a tumor suppressor." (PMID 36034466, 2022). "E2F1 has been reported to affect cell growth by regulating NF-κB, thereby enhancing tumor proliferation and anti-apoptosis." (PMID 36424626, 2022). "To date, the role of E2F-1 in carcinogenesis is still controversial; E2F-1 can act as either an oncogene or tumor suppressor gene according to the published literature." (PMID 35303867, 2022). "It is also reported that knockdown of E2F1 inhibited tumor cell proliferation and promoted apoptosis in castration-resistant prostate cancer (CRPC) by regulating TMOD2 and AIF1L expression." (PMID 35392496, 2022). "E2F1, which interacts with the retinoblastoma tumor suppressor, has been shown to have a role in promoting cellular senescence." (PMID 35245177, 2022). "We identified the transcription factor E2F1 as a key regulator of tumor cell proliferation and self-renewal in only a subset of gliomasphere cultures predicted to be E2F1 signaling dependent." (PMID 36213002, 2022).
tumor (continued). "By taking the intersection of the two cohorts, we identified 26 upregulated TFs with twofold upregulation in tumour tissues compared with NT liver tissues, although four of them (E2F1, FOXM1, LIN28B, and MYCN) were excluded for overrepresentation." (PMID 36008383, 2022). "For example, E2F1 was reported to promote tumor growth, invasion and metastasis of CRC cells by activating the ribonucleotide reductase small subunit M2 (RRM2) transcription." (PMID 35069909, 2022). "E2F8 is a transcription repressor that antagonizes E2F1 in regulating the cell cycle, apoptosis, and tumor promotion." (PMID 36499314, 2022). "In accordance with this, restoration of miR-532 weakened the tumor-promoting effect of E2F1 in GC cells and blocked tumor growth in vivo." (PMID 35440106, 2022). "Knockdown of E2F1 was followed by increased expression of the tumor suppressor miR-34c, i.e., inhibition of tumor growth and proliferation at the G1/S checkpoint." (PMID 36316351, 2022). "Taken together, these results suggest that YAP1 regulates the expression of multiple genes involved in angiogenesis through the mediation of E2F1 transcription factor in the tumor cells." (PMID 35937460, 2022). "Our in vivo work also validated the functional significance of E2F1 in tumor formation capacity in the predicted samples." (PMID 36213002, 2022). "Conversely, HK301 E2F1 KD cells showed limited tumor formation in vivo while animals injected with HK301 control cells showed tumors in four out of five mice." (PMID 36213002, 2022). "E2F1 expression was lower in the tumor-free liver group and significantly increased in the 4TLM and 67NR groups compared to the tumor-free group." (PMID 36142156, 2022). "As a result of the TCGA pan-cancer transcriptome data, the expression levels of KAT2A and E2F1 were significantly up-regulated in 16 and 20 kinds of tumor tissues compared with normal tissues, respectively." (PMID 36292703, 2022). "In contrast, E2F1, an important transcription factor and tumor promoter, directly inhibits miR-34c expression in GC cell lines." (PMID 36316351, 2022). "In this study, we showed that E2F1 act as a tumor promoter in GC progression and correlate with poor prognosis of GC patients." (PMID 35440106, 2022). "Consistently, qRT-PCR analysis of 80 paired HCC patient tissues indicated that tumour tissues had a higher level of E2F1 expression than peritumour tissues." (PMID 35844791, 2022). "Here, TCGA database analysis, microarray immunohistochemical technique and western blot showed that E2F1 was highly upregulated in clinical GC tissues and correlated with tumor malignancy." (PMID 35440106, 2022). "One of these promising mutants is ICOVIR-7 that also has a modified E2F1-promotor replacing the E1A-promoter in addition to an RGD-4C motif in the HI-loop of the fibre domain to enhance tumour selectivity, integrin-binding and entry into tumour cells." (PMID 35813830, 2022). "Similar results were found in NB4 tumours, in which LncSIK1 enhancement exerted a minor effect on E2F1 at the protein and mRNA levels during tumour growth." (PMID 35092119, 2022). "TMPO-AS1 silencing has substantially suppressed tumor growth, while up-regulation of E2F1 has eliminated the inhibitory effects on tumor growth resulted from TMPO-AS1 silencing." (PMID 36467407, 2022). "E2F1, an established transcription factor in cell cycle regulation, exerts tumour‐suppressive activity and anti‐proliferative properties." (PMID 34428336, 2021). "In particular, patients with more than 2 copies of E2F1 had less lymph nodes-positive (p = 0.04) and prevalently a bilateral tumour (p = 0.04), and, additionally, they had positive BC family history (p = 0.001)." (PMID 33691613, 2021). "Further, circSDHC promotes ccRCC progression and metastasis by acting as a sponge for miR-127-3p, which is a tumor suppressor that downregulates the activity of CDKN3/E2F1 axis." (PMID 33468140, 2021).
tumor (continued). "Other mutations within PyMT E2F1 KO tumors include COL5A2, with collagen V being a component of the interstitial matrix, COL6A1-3, with collagen VI being abundant in the tumor invasive front and several integrin and cadherin genes." (PMID 33947907, 2021). "Compared to the normal adjacent lung tissues, the expression of E2F1 and of its target genes was significantly high in tumour tissues." (PMID 33883577, 2021). "The results revealed significant correlations between E2F1 expression level and differentiation degree (p < 0.05), Tumor size (p < 0.05), and T stage (p < 0.05)." (PMID 33986804, 2021). "Results showed that the knockout of TMPO-AS1 significantly suppressed tumor growth compared to the control group, whereas the overexpression of E2F1 abolished the inhibitory effect on tumor growth induced by the knockout of TMPO-AS1." (PMID 33816295, 2021). "Our studies illustrated that miR-1258 functioned as a tumor suppressor in GBM by directly targeting E2F1, subsequently inhibiting PCNA and MMP2 transcriptions, which contributed to new potential targets for GBM therapy and other E2F1-driven cancers." (PMID 34079762, 2021). "On the other hand, the tumor suppressive effect of E2F1 can be explained by E2F1-mediated apoptosis and growth arrest." (PMID 34136392, 2021). "We also demonstrate that ESRP1 is paradoxically downregulated in the hypoxic tumor milieu despite the abundance of E2F1." (PMID 34362878, 2021). "In contrast, the tumor suppressor ARID1A inhibits cancer stemness of squamous cell carcinoma by antagonizing pRb/E2F1/c-Myc pathway, ultimately impairs resistance to chemotherapy." (PMID 33456565, 2021). "The most significantly overexpressed gene in TMBhigh tumors was E2F1 (p = 0.0098), which encodes a transcription factor essential for cell cycle, DDR, and tumor suppression regulation." (PMID 34172722, 2021). "Deregulated E2F1 acts as a driving force in GC progression and promotes tumor invasion and metastasis independently from its other cellular activities." (PMID 35082831, 2021). "LINC00461 was reported to be highly expressed in lung tumor, and its knockdown suppressed the tumor cells' proliferation and metastasis via miR-4478/E2F1." (PMID 34966465, 2021). "Taken together, these findings indicated that the synergistic co-overexpression of TERT, E2F1, and MYC in PCa is strongly associated with poor prognosis, tumor progression, metastasis, and patient survival." (PMID 34858826, 2021). "The western blot results on both ESCC cells and tumor tissues revealed that silencing of E2F1 blocked the PI3K/AKT signaling pathway, which was restored by miR-375 inhibitor." (PMID 34699320, 2021). "To better comprehend the tumor‐suppressive function of miR-1258 mechanistically, we identified E2F1 as one of the direct and functional targets for miR-1258 in GBM." (PMID 34079762, 2021). "Overexpression of E2F1 can promote cell proliferation and tumor development, but deletion of E2F1 in mice leads to tumorigenesis, suggesting that E2F1 also plays a vital role in tumor inhibition." (PMID 34499617, 2021). "The protein levels of Wnt10B and β‐catenin in tumor tissues were reduced by miR‐107 mimic or sh‐E2F1." (PMID 34758200, 2021). "Immunofluorescence staining revealed lower levels of Ki67 and higher levels of E2F-1 in tumour tissues of the avasimibe group than those of the control group." (PMID 34461908, 2021). "Conversely, the tumor-promoting activity of PSMD14 in vivo was counteracted by the stable knockdown of E2F1." (PMID 33456565, 2021). "We previously demonstrated altered phenotypic characteristics upon ablation of E2F1 within Neu and PyMT models, including changes in growth rate and tumor latency for the primary tumors." (PMID 33947907, 2021). "Our results suggest that avasimibe can suppress tumour proliferation and metastasis via the E2F-1 signalling pathway." (PMID 34461908, 2021).